GDF10 (growth differentiation factor 10)
Diseases named in the same sentence as GDF10 in open-access papers (continued):
Sharing a sentence is not in itself a finding about the gene and the disease.
liver fibrosis (2 papers, 2025). "Through gain- and loss-of-function experiments, we show that Gdf10 overexpression attenuates liver fibrosis by competitively binding TβR2, blunting SMAD2/3 phosphorylation, and suppressing TGFβ1-driven ECM deposition." (PMID 41281741, 2025). "Among the extracellular region‐related DEGs, GDF10 was identified as a novel liver fibrosis‐associated cytokine." (PMID 40125634, 2025). "By analyzing transcriptome datasets from mouse fibrotic livers, we identified GDF10 as a liver fibrosis‐associated cytokine." (PMID 40125634, 2025). "Collectively, these data demonstrate that GDF10 effectively ameliorates diet-induced MASH associated liver fibrosis in vivo." (PMID 41281741, 2025). "The inhibitory effects of GDF10 on TGF‐β‐induced HSC activation impelled us to examine the role of GDF10 in liver fibrosis." (PMID 40125634, 2025). "The discovery of GDF10 as a HSC-derived factor capable of attenuating liver fibrosis through dual modulation of TGF-β signaling and metabolic reprogramming represents a significant advancement in our understanding of antifibrotic mechanisms." (PMID 41281741, 2025). "To further investigate the functional role of GDF10 in liver fibrosis progression, we employed a lentiviral system delivering shRNA to knock down Gdf10 (Gdf10-KD) expression in vivo." (PMID 41281741, 2025). "To further delineate the role of GDF10 in inhibiting liver fibrosis, we first analyzed scRNA-seq data of CCl4-induced mouse liver and it revealed that Gdf10 was more specifically expressed in quiescent HSCs, with less coincidence with canonical aHSC markers." (PMID 41281741, 2025). "Loss of GDF10 function promotes HSC activation and exacerbates liver fibrosis in mice, while gain of GDF10 function alleviates this pathological condition." (PMID 40125634, 2025). "Histopathological assessment revealed significant improvement in liver fibrosis in Gdf10-OE mice, which was further supported by decreased expression of fibrogenic genes at both mRNA and protein levels." (PMID 41281741, 2025). "We subsequently dissected the significance of GDF10 in liver fibrogenesis and explored its potential clinical significance in the treatment of liver fibrosis in mice." (PMID 40125634, 2025). "Histological analysis also showed that Gdf10-KD mice had exacerbated liver fibrosis compared to control mice." (PMID 41281741, 2025). "Loss of GDF10 promoted HSC activation and liver fibrosis, whereas gain of GDF10 alleviated this pathological condition." (PMID 40125634, 2025). "Notably, Gdf10 expression patterns closely aligned with those of established HSC markers in liver fibrosis." (PMID 41281741, 2025). "We next evaluated the therapeutic potential of GDF10 in liver fibrosis." (PMID 40125634, 2025). "Importantly, Gdf10-expressing AAV treatment inhibited the SMAD2-mediated liver fibrosis pathway in the HFFC diet-induced MASH model." (PMID 41281741, 2025). "This study highlights the profound therapeutic potential of GDF10 in patients with liver fibrosis." (PMID 40125634, 2025). "Additionally, BMPR2/ALK3 heterodimer was essential for GDF10 to inhibit liver fibrosis." (PMID 40125634, 2025). "In conclusion, the results demonstrate that administration of GDF10 effectively attenuates HSC activation and shows promising outcomes in the reversal of mouse liver fibrosis with different etiologies." (PMID 40125634, 2025). "In conclusion, GDF10 is an autocrine suppressor of HSC activation and a potential therapeutic target for the treatment of liver fibrosis." (PMID 40125634, 2025). "Consistently, recombinant GDF10 protein treatment ameliorated CCl4‐induced, AMLN diet‐induced, and MCD diet‐induced liver fibrosis." (PMID 40125634, 2025). "Thus, pharmacologically targeting GDF10 could be explored in the treatment of liver fibrosis." (PMID 40125634, 2025).
liver fibrosis (continued). "In summary, autocrine GDF10 activates BMPR2/ALK3‐SMAD1/5/8‐SMAD7 pathway to counteract the TGF‐β‐SMAD2/3 pathway in HSCs, thereby inhibiting HSC activation and preventing liver fibrosis." (PMID 40125634, 2025). "In this study, we identified GDF10 as a critical regulator of HSC activation and a promising therapeutic target for liver fibrosis." (PMID 40125634, 2025). "This study identifies autocrine GDF10 activates BMPR2/ALK3‐SMAD1/5/8‐SMAD7 pathway to counteract the TGF‐β‐SMAD2/3 pathway in HSCs, thereby inhibiting HSC activation and preventing liver fibrosis." (PMID 40125634, 2025). "Our findings posited GDF10 as a dual-functional modulator of TGF-β signaling and HSC metabolic plasticity, offering a precision therapeutic strategy for liver fibrosis." (PMID 41281741, 2025). "We also examined the therapeutic potential of GDF10 in AMLN diet‐induced and MCD diet‐induced mouse liver fibrosis." (PMID 40125634, 2025). "Our findings establish GDF10 as a dual-function modulator of TGF-β signaling and HSC metabolism, offering a targeted therapeutic strategy for liver fibrosis." (PMID 41281741, 2025). "To further explore the role of GDF10 in HSC activation and liver fibrosis, we generated HSC‐specific Gdf10 transgenic (Gdf10TG) mice by crossing Lrat‐Cre mice with the Gdf10 LoxP mice harboring the LoxP‐Stop‐LoxP‐Gdf10 cassette in the Rosa26 locus." (PMID 40125634, 2025). "Moreover, recombinant GDF10 protein treatment suppresses HSC activation and alleviates liver fibrosis in mice." (PMID 40125634, 2025). "In the liver, GDF10 expression is enriched in HSCs, yet its functional significance in liver fibrosis and HSC biology has not been explored." (PMID 41281741, 2025).
nasopharyngeal carcinoma (2 papers, 2022 to 2023). A carcinoma arising from the nasopharyngeal epithelium. "In nasopharyngeal carcinoma, GDF10 is regulated downward due to its promoter's aberrant methylation, which can be reversed when treated with 5-Aza-2′-deoxycytidine." (PMID 36262352, 2022). "Additionally, GDF10 inhibits cell proliferation and epithelial-mesenchymal transition in nasopharyngeal carcinoma." (PMID 37868033, 2023).
triple-negative breast carcinoma (2 papers, 2023 to 2025). An invasive breast carcinoma which is negative for expression of estrogen receptor (ER), progesterone receptor (PR), and human epidermal growth factor receptor 2 (HER2). "In triple negative breast cancers, growth differentiation factor-10 (GDF10), a member of the TGF-β superfamily, was downregulated in tumour samples." (PMID 37685308, 2023).
atherosclerosis (1 paper, 2022). A disease characterized by the build-up of fatty material and calcium deposition in the arterial wall resulting in partial or complete occlusion of the arterial lumen. "The finding of the present study identified osteoblast factor GDF10 as one of the specific factors implicated in the regulation of the VSMCs osteoblast/chondrocyte switch with likely detrimental implications in atherosclerosis disease severity." (PMID 35163719, 2022). "In conclusion, our results show that osteoblast factor GDF10 has a likely detrimental role given our finding that GDF10-positive VSMC osteoblast-like cells are present in areas of human vascular calcification and are associated with CAD events in human atherosclerosis." (PMID 35163719, 2022). "The present study further extended the knowledge about GDF10 and its role in cardiovascular pathology showing that GDF10 could mediate VSMC transdifferentiation to osteogenic-like cells, with a likely detrimental role in atherosclerosis plaque stability." (PMID 35163719, 2022).
chronic kidney disease (1 paper, 2024). Impairment of the renal function secondary to chronic kidney damage persisting for three or more months. "Furthermore, we demonstrated an increase in circulating GDF10 in patients with chronic kidney disease with clinically defined severe VC, as assessed by coronary artery calcium score." (PMID 39307303, 2024).
Cirrhosis (1 paper, 2025). A chronic disorder of the liver in which liver tissue becomes scarred and is partially replaced by regenerative nodules and fibrotic tissue resulting in loss of liver function. "Using single-cell RNA sequencing, we demonstrate that Gdf10 expression is restricted to HSCs and inversely correlates with fibrotic activation across animal models and human cirrhosis." (PMID 41281741, 2025).
coronary artery calcification (1 paper, 2024). Calcification of the coronary artery, used as a measure of coronary atherosclerosis, a risk factor for myocardial infarction. "Given the established role of circulating osteogenic proteins in the development of arterial calcification, we next examined circulating GDF10 levels in a cohort of 18 patients with CKD having severe VC, as assessed by coronary artery calcification (CAC) score of >200." (PMID 39307303, 2024).
endometrial cancer (1 paper, 2022). Primary or metastatic malignant neoplasm involving the endometrium (mucous membrane that lines the endometrial cavity). "This investigation aims to identify GDF10 methylation site-associated genes that are closely associated with endometrial cancer (EC) patients' survival based on normal and UCEC samples from the UCSC Xena database." (PMID 36262352, 2022).
Ewing sarcoma (1 paper, 2014). A small round cell tumor that lacks morphologic, immunohistochemical, and electron microscopic evidence of neuroectodermal differentiation. "Thus, four unique genes (GDF10, OSM, APC, and HOXA11) were selected that were the most significantly differentially methylated in the Ewing’s sarcoma samples." (PMID 25202378, 2014).
glioblastoma (1 paper, 2014). The most malignant astrocytic tumor (WHO grade IV). "Among these genes, GDF10 has been reported to have a gender-dependent effect on glioblastoma progression and survival." (PMID 25202378, 2014).
injury (1 paper, 2022). Damage inflicted on the body as the direct or indirect result of an external force, with or without disruption of structural continuity. "However, up-regulation of GDF-10 by erythropoieti has previously shown to promote axonal sprouting for neurological recovery after brain injury." (PMID 36714584, 2022).
Insulin resistance (1 paper, 2019). Increased resistance towards insulin, that is, diminished effectiveness of insulin in reducing blood glucose levels. "The GDF10 and TNN are novel biomarkers for the development of insulin resistance." (PMID 30678306, 2019).
liver disease (1 paper, 2025). "As the field moves toward precision medicine approaches for liver disease, GDF10 emerges as both a promising therapeutic agent and a valuable tool for elucidating the complex interplay between signaling pathways and cellular metabolism in fibrosis pathogenesis." (PMID 41281741, 2025).
mesothelioma (1 paper, 2011). A usually malignant and aggressive neoplasm of the mesothelium which is often associated with exposure to asbestos. "Lastly, the gender-dependent association between Gdf10 and progression-free survival is in agreement with reports of copy number loss of Gdf10 in mesothelioma." (PMID 21649900, 2011).
metastatic cancers (1 paper, 2021). A carcinoma which has spread from the original site of growth to another anatomic site. "BMP5 and GDF10 (BMP3b) expression was particularly altered by changes in ERK1/2 activation, although the functions of these genes in breast and metastatic cancers have not been well characterized." (PMID 34588427, 2021).
oral cancer (1 paper, 2020). "Previously, we found a set of retinoid signaling related genes, including ADHFE1, ALDH1A2, CRBP1, PAX9, GDF10, TGFBR3, and PPARγ were frequently hypermethylated and downregulated in OSCC patient samples, suggesting the severe molecular defects in RA metabolism in oral cancer." (PMID 32238162, 2020).
prostatic tumor (1 paper, 2021). "All these results indicated that PGM5-AS1 overexpression suppressed the growth of xenograft prostatic tumor via the miR-587/GDF10 axis." (PMID 33407592, 2021).
tumor (27 papers, 2007 to 2026). "Also osteoclast-secreted factors such as growth differentiation factor 10 (GDF10) and TGFβ2 are implicated in inducing tumor cell dormancy." (PMID 36757577, 2023). "Some studies have shown that GDF10 exerts tumor-suppressive effects in a range of cancer types and also plays a protective role against muscle wasting." (PMID 42111348, 2026). "CCL14, FYN, NOD1, and GDF10 mRNA expressions were decreased in tumor tissues compared with the adjacent non-tumor tissues." (PMID 38602568, 2024). "Another two TRIGs in this model, SCGB3A1 (alias HIN-1) and GDF10, are both considered as tumor immune suppressors, which are correlated with clinicopathological variables." (PMID 35620481, 2022). "CAF promote stromal fibroblast activation and the proliferation and migration of tumor cells by secreting GDF10." (PMID 33657265, 2022). "It was concluded that the higher expression of GDF10 was at a high level in both the OSCC tumor sample and xenograft models co‐injected with HSC3, with CAF stably expressed by si‐NC, according to immunohistochemistry." (PMID 33657265, 2022). "The expression level of GDF10 in tumor tissues of OSCC patients with a high expression of LOC100506114 was significantly higher than that of OSCC patients with a low expression of LOC100506114." (PMID 33657265, 2022). "Among 11 BMPs, BMP3 and BMP8A expression levels were upregulated, and 5 BMPs (BMP2, BMP5, GDF5, BMP6, and GDF10) downregulated in tumor tissues compared with normal tissues." (PMID 34745928, 2021). "The violin plot describing the distribution of BMP expression in tumor and normal tissues suggested that GDF10 was the most significantly downregulated BMP, and the downregulating degree of ACVRL1 was obvious from the violin plot of BMPRs." (PMID 34745928, 2021). "Accordingly, we tested in the study functional relevance of PGM5-AS1/miR-587/GDF10 axis in PCa cells and xenografts tumor." (PMID 33407592, 2021). "Tumor xenografts derived from GDF10-overexpressing cells (GDF10-OE group) were significantly smaller, and lighter than those derived from NC cells." (PMID 31147529, 2019). "In summary, these observations suggested that GDF10 functions as a tumor suppressor in mammary epithelial cells by promoting cell cycle arrest and inhibiting EMT." (PMID 31147529, 2019). "By implementing under- and over-expression experiments in vitro we showed for the first time that GDF10 acts as a tumor suppressor in TNBC by inducing cell cycle arrest, and inhibiting proliferation and invasion of immortalized cells." (PMID 31147529, 2019). "Overall, our studies suggest that GDF10 acts as a tumor suppressor in mammary and other epithelial cells." (PMID 31147529, 2019). "The expression of GDF10 was significantly downregulated in tumor tissues compared with normal, matched controls." (PMID 31147529, 2019). "In summary, the current study showed that GDF10 is downregulated in both TNBC patient samples and immortalized cell lines, and its loss correlates with tumor aggressiveness." (PMID 31147529, 2019). "Similarly, increased intramuscular rAAV6:GDF10 expression exacerbated skeletal muscle wasting in C-26 tumor-bearing mice." (PMID 42111348, 2026). "It is well known that GDF10 is usually suppressed in tumor cells." (PMID 33657265, 2022). "Finally, the expression of TGFβR1 in GDF10‐treated tumor cells was upregulated, which is consistent with the upregulation of TGFβR1 expression in the treatment of CAF‐CM." (PMID 33657265, 2022). "In addition, MMP1, MMP2 and MMP9, which are closely related to tumor cell migration, were significantly upregulated in the GDF10‐treated group." (PMID 33657265, 2022). "CAFs promote tumor invasiveness and remodel the stroma from a mature to an immature state by the deposition of glycosaminoglycans through growth differentiation factor (GDF10) secretion." (PMID 35418058, 2022).
tumor (continued). "PGM5-AS1 overexpression was successfully transduced into the tumors of nude mice, according to the downregulated miR-587 expression and upregulated PGM5-AS1 and GDF10 expression observed in tumor tissues from nude mice injected with cells transduced with PGM5-AS1 overexpression plasmid." (PMID 33407592, 2021). "Thus, our in vivo data are consistent with our in vitro findings and further support the conclusion that GDF10 serves as a tumor suppressor that is downregulated in TNBC." (PMID 31147529, 2019). "Importantly, GDF10 expression in clinical samples correlated negatively with tumor proliferation (Ki67 staining) and TNM stage." (PMID 31147529, 2019). "In parallel, IHC staining showed reduced Ki67 expression in tumor sections from the GDF10-OE group." (PMID 31147529, 2019). "In addition, overexpression of GDF10 reduced tumor burden and induced apoptosis in a TNBC xenograft mouse model." (PMID 31147529, 2019). "We conducted RNA-Seq analysis to identify differentially expressed genes (DEGs) between clinical TNBC specimens and tumor-matched controls and found significant downregulation of growth differentiation factor-10 (GDF10), a member of the transforming growth factor-β (TGF-β) superfamily." (PMID 31147529, 2019). "In LUAD studies, WGCNA combined with immune-related genes identified four key hub genes: CBLC, FABP4, GDF10, and LTBP4, showing significant differential expression between tumor and normal samples." (PMID 40766337, 2025). "The interaction of GDF10 with the transcription factor RUNX family transcription factor 2 further enhanced the growth and migration of OSCC tumor cells by activating the TGFβRI/Smad3/ERK pathway." (PMID 33657265, 2022). "To verify how the effect of GDF10 on the transformation of CAF and tumor cell growth, we determined the expression of α‐SMA and FAP in CAF transfected with si‐GDF10 by qPCR." (PMID 33657265, 2022). "Meanwhile, GDF-10 can activate the TGFBR1/Smad3/ERK pathway to promote the growth and migration of tumor cells, and further regulate the recruitment and activation of Smad family transcription factors." (PMID 36714584, 2022). "In the present study, we found that GDF10 also promotes the growth and migration of OSCC tumor cells by activating the TGFβRI/Smad3/ERK pathway." (PMID 33657265, 2022). "To demonstrate further that the expression of GDF10 in CAF promotes tumor cell migration, we added tumor cells with exogenous human recombined GDF10." (PMID 33657265, 2022). "To demonstrate that LOC100506114‐reprogrammed CAF, promoted tumor cell migration and growth by secreting GDF10, we treated OSCC cell line SCC4 with the CM from CAF transfected with si‐GDF10 or si‐NC." (PMID 33657265, 2022). "Last, the correlation among eight deBMPs/BMPRs was analyzed in tumor tissues of TCGA-LUAD, BMP5, and GDF10, as prognostic factors were well correlated with other deBMPs/BMPRs." (PMID 34745928, 2021). "We found that growth differentiation factor-10 (GDF10), a member of the TGF-β superfamily, was downregulated in tumor samples." (PMID 31147529, 2019). "Systemic rAAV6:GDF10 administration to mice did not alter primary tumor growth; however, metastatic burden was increased in the mice bearing 4T1.2 tumors." (PMID 42111348, 2026). "In addition, we demonstrated that GDF10 promotes the functional transformation of normal human NF into CAF by LOC100506114 binding to transcription factor RUNX2, to support tumor cell growth, invasion and metastasis." (PMID 33657265, 2022). "The results showed that the expression of GDF10 in CAF was much higher than that of other cells, and the expression of GDF10 in some tumor cell lines (such as CAL27 and HB) was lower than that of normal epithelial cells." (PMID 33657265, 2022). "Furthermore, over-expression of GDF-10 brings about the up-regulation of p-SMAD3, consequently promoting the activation of stromal fibroblasts and the proliferation and migration of tumor cells." (PMID 36714584, 2022).